KLF5 (KLF transcription factor 5)
Diseases named in the same sentence as KLF5 in open-access papers (continued):
Sharing a sentence is not in itself a finding about the gene and the disease.
lung adenocarcinoma (6 papers, 2011 to 2025). A carcinoma that arises from the lung and is characterized by the presence of malignant glandular epithelial cells. "CPTAC and TCGA database were analyzed to determine the clinical association of α-Catulin, KLF5, and stemness-associated signatures in lung adenocarcinoma." (PMID 35154481, 2022). "Since the regulation of tumor-associated signaling pathways by KLF5 is USP38-dependent, USP38 becomes a potential therapeutic target for lung adenocarcinoma, providing a new direction for the precise treatment of lung adenocarcinoma." (PMID 40936898, 2025). "In this study, we demonstrate that MLK4 gene overexpression serves as an oncogenic event in lung adenocarcinoma, and dissect the role of the transcription factor KLF5 in driving MLK4 regulation." (PMID 37407566, 2023). "Taken together, our results suggest that the 3-gene signature of CTNNAL1 plus ILK plus KLF5 can be used to predict the outcome of patients with lung adenocarcinoma." (PMID 35154481, 2022). "Our analyses of human lung adenocarcinoma specimens from the CPTAC dataset revealed higher expression of the KLF5 protein in high-α-Catulin-expressing tumors than in low-α-Catulin-expressing tumors." (PMID 35154481, 2022). "Accordingly, increased protein expression of KLF5 is observed in clinical specimens of lung adenocarcinoma with high expression of α-Catulin compared to specimens with low α-Catulin-expression." (PMID 35154481, 2022). "Importantly, we identify a CTNNAL1/ILK/KLF5 three-gene signature for predicting poor overall survival in patients with lung adenocarcinoma." (PMID 35154481, 2022). "Furthermore, it is noteworthy that in lung adenocarcinoma, KLF5 not only regulates the KLF5-MLK4-PCK1 signaling axis but also influences drug metabolism pathways associated with Cytochrome P450 enzymes, highlighting the importance and complexity of KLF5 in regulating lung adenocarcinoma development." (PMID 40936898, 2025). "Co-expression of KLF5 and MLK4 were observed in lung adenocarcinoma with diverse patterns of invasion." (PMID 37407566, 2023). "Besides, KLF5 and MLK4 upregulation in lung adenocarcinoma led to a worse prognosis, verifying the importance of KLF5-MLK4 axis in lung cancer." (PMID 37407566, 2023). "Together with the findings that KLF5, MLK4, and PCK1 appeared to be correlated in their expressions and predict a worse prognosis in lung adenocarcinoma, the study proposed a model of KLF5-MLK4-PCK1 signaling cascade that promotes glucose metabolism and tumorigenesis." (PMID 37407566, 2023). "Finally, the promoter analysis of MLK4 unravelled a binding site of transcription factor KLF5, which in turn, positively regulated MLK4 expression in lung adenocarcinoma." (PMID 37407566, 2023). "Similarly, in lung adenocarcinoma, USP38 also exerts deubiquitination activity on KLF5." (PMID 40936898, 2025).
sarcopenia (6 papers, 2016 to 2024). Progressive decline in muscle mass due to aging which results in decreased functional capacity of muscles. "Since information on KLF5 is limited, further research is needed to understand its genetic regulation concerning sarcopenia." (PMID 39795113, 2024). "Nevertheless, KLF5 expression increases with aging, and sarcopenia development positively correlates with the expression of the atrophy-related ubiquitin ligase genes FBXO32 and TRIM63." (PMID 39795113, 2024). "A previous study on genetic markers for sarcopenia identified the loci near FTO, ESR1, NOS3, KLF5, and HLA-DQA1 to be associated with physical phenotypes, such as low handgrip strength and decreased LBM24–26." (PMID 35241739, 2022). "It would also be interesting to know whether Klf5-mediated pathways are involved in such pathological conditions as sarcopenia." (PMID 27743478, 2016).
asthma (5 papers, 2017 to 2022). "We conducted this study aiming at exploring the effect of Histone deacetylase 4 (HDAC4)-mediated Kruppel-like factor 5 (KLF5)/Slug/CXC chemokine ligand-12 (CXCL12) axis on the development of asthma in regulation of airway inflammation and remodeling." (PMID 34118928, 2021). "Collectively, HDAC4 deacetylates KLF5 to upregulate Slug and CXCL12, thereby causing airway remodeling and facilitating progression of asthma." (PMID 34118928, 2021). "In the current study, we explored the contributory role of HDAC4-mediated KLF5/Slug/CXCL12 axis in the development of asthma." (PMID 34118928, 2021). "We thus conclude that the interaction between HDAC4 and KLF5 through deacetylation plays an important role in asthma development." (PMID 34118928, 2021). "Furthermore, we demonstrated that KLF5 bound to the promoter of Slug to increase its expression in asthma, thereby reducing airway inflammation and remodeling." (PMID 34118928, 2021). "Next, we explored whether KLF5 bound to the promoter of Slug to affect its transcription during asthma development." (PMID 34118928, 2021). "In addition, we found that HDAC4 deacetylated KLF5 to promote its transcription in asthma." (PMID 34118928, 2021). "For example, histone deacetylase 4 can mediate KLF5 deacetylation to upregulate CXCL12, leading to airway remodeling and promoting the progression of asthma." (PMID 35619697, 2022). "The expression of HDAC4 was upregulated in lung tissues of asthmatic mice, and it could deacetylate Kruppel-like factor 5 (KLF5) to upregulate Slug and CXC chemokine ligand-12 (CXCL12), thus triggering airway remodeling and promoting progression of asthma." (PMID 35280995, 2022). "For instance, KLF5 was found to accelerate the inflammation of human bronchial epithelial cells BEAS-2B and HBE135-E6E7 as well as to facilitate the proliferation and migration of BSMCs, thereby promoting the progression of asthma." (PMID 34118928, 2021).
glioma (5 papers, 2012 to 2025). A benign or malignant brain and spinal cord tumor that arises from glial cells (astrocytes, oligodendrocytes, ependymal cells). "In order to determine whether the expression of Hif-2αinfluenced the expression of Klf5 in glioma cells, we transduced Rt-glioma cells with an inducibly-expressed variant of Hif-2α(Hif-2αP531A) that is degradation-resistant under normoxia." (PMID 22905089, 2012). "Our results also raise the possibility that Klf5 mediates certain Hif-dependent downstream functions within glioma." (PMID 22905089, 2012). "We also find that Klf5, a transcription factor important to vascular remodeling, was regulated by hypoxia in glioma." (PMID 22905089, 2012). "To provide additional evidence that Klf5 can respond downstream of Hif-2α in glioma cells, we expressed a shRNA designed to specifically silence Hif-2α in Hu-glioma cells." (PMID 22905089, 2012). "Consistent with our in vitro experiments, a quantitative analysis of total tumor transcript levels indicated that Dox-induced Egln3 reduced Vegf by ≈80%, Klf5 by ≈90% and Oct4 by ≈90% in Rt-gliomas." (PMID 22905089, 2012). "Low levels of Egln3 induction (0.25μg/mL Dox) reduced the transcription of Klf5 and the Hif-2α transcriptional target, Oct4 by ≈50% and ≈70%, respectively within Hu-glioma cells relative to hypoxia-treated controls." (PMID 22905089, 2012). "Similar to Rt-glioma cells, Hu-glioma cells upregulated both Hif-2αand Klf5 upon hypoxic insult." (PMID 22905089, 2012). "In fact, Egln3H196A evoked increases in both Klf5 and Oct4 that we speculate may be due to potential dominant-negative effects of Egln3H196A expression within glioma upon other signaling pathways (e.g. Egln1)." (PMID 22905089, 2012). "Induced expression of Hif-2αP531A up-regulated Klf5 in Rt-glioma cells under normoxic conditions." (PMID 22905089, 2012). "Some studies have shown that the molecular mechanism of glioma formation involved HDAC4-mediated SP1 and KLF5 deacetylation in selective MKK7 transcription and oncogenic JNK/c-Jun cascade activation." (PMID 35359455, 2022). "Interestingly, MKK7 transcription critically depends on the deacetylation of the transcription factors SP1 and Kruppel-like factor-5 (KLF5) by HDAC4, the inhibition of which is paramount in suppressing the oncogenic JNK/c-Jun cascade involved in glioma cells." (PMID 33117806, 2020).
ischemic cardiomyopathy (5 papers, 2022 to 2025). Ischemic cardiomyopathy is a cardiomyopathy in which a weakness in the muscle of the heart due to inadequate oxygen delivery to the myocardium with coronary artery disease being the most common cause. "Previously identified KLF-5 is a prohypertrophic factor that is increased in patients with terminal heart failure and mice with ischemic cardiomyopathy." (PMID 36836777, 2023). "When using the pharmacological inhibitor of Klf-5, ML264, an improvement in echocardiographic parameters, such as ejection fraction, was observed, as well as a reduction in end-diastolic and systolic volume, exerting a protective effect against ischemic cardiomyopathy." (PMID 36836777, 2023).
liver fibrosis (5 papers, 2012 to 2025). "In the liver, KLF5 is involved in the fibrotic response, as shown by the elevation of KLF5 mRNA expression induced by dimethylnitrosamine, causing liver fibrosis." (PMID 35457114, 2022). "It was also found that KLF5 promoted collagen deposition in the hepatic stellate cells of liver fibrosis rat models, whereas KLF4 inhibited the synthesis of collagen in human hepatic stellate cells." (PMID 31829402, 2019). "Additionally, dimethylnitrosamine induced significant increase in KLF5 mRNA expression and induced liver fibrosis, suggesting a role for KLF5 in the fibrotic response." (PMID 33523554, 2021). "In contrast, “hepatic fibrosis/hepatic stellate cell activation” was the most significantly enriched (p<10−12) pathway among the genes exclusively modulated by Klf5, indicative of a general fibrotic response such as that observed in cultured human keratocytes exposed to TGF-β." (PMID 23024760, 2012).
aortic aneurysm (4 papers, 2020 to 2026). A ruptured aneurysm located in the wall of the proximal portion of the descending aorta proceeding from the arch of the aorta. "We show that upregulation of Golph3l by Klf5 facilitates TNF‐α and TNFSF12 secretion from AngII‐stimulated VSMCs by modulating the Golgi morphology, which is essential for AIP in VSMCs and aortic aneurysm formation." (PMID 41317401, 2026).
endometrial cancer (4 papers, 2019 to 2021). Primary or metastatic malignant neoplasm involving the endometrium (mucous membrane that lines the endometrial cavity). "These include a local low-throughput 3C approach, which we have previously used to identify chromatin looping between CV-containing regions and KLF5 at the 13q22.1 endometrial cancer risk locus." (PMID 31561579, 2019). "Endometrial cancer GWAS risk variation has been found to loop to KLF5 in data generated by a local 3C-based technique, an interaction which we did not observe in our HiChIP analyses." (PMID 31561579, 2019). "Three SNPs have been identified in or around KLF5 that are associated with endometrial cancer." (PMID 32066633, 2020). "Our HiChIP approach had much higher resolution (due to the use of a restriction enzyme producing smaller fragments) and closer examination of the HiChIP data at 13q22.1 revealed a KLF5 promoter interaction in JHUEM-14 cells that looped to an anchor 23 bp from endometrial cancer risk CV rs9600103." (PMID 31561579, 2019). "Metapristone decreased the expression of miR-492 and its target genes Klf5 and Nrf1, leading to endometrial cancer cell growth inhibition in vitro and in vivo." (PMID 33413440, 2021). "More importantly, this study suggested that metapristone inhibited endometrial cancer cell growth via miR-492/Klf5/Nrf1 axis, which provided a new mechanism of antitumor effect of metapristone on endometrial cancer for the clinical application." (PMID 33413440, 2021). "Mechanically, miR-492 and its target genes Klf5 and Nrf1 were highly expressed in the endometrial cancer cell lines, which promoted cell proliferation and inhibited cell apoptosis." (PMID 33413440, 2021). "Secondly, the mechanical relationship between Klf5/Nrf1 and cell proliferation or apoptosis with the treatment of metapristone on endometrial cancer has still indistinct." (PMID 33413440, 2021). "Taken together, all the results showed that metapristone inhibited the endometrial cancer cell growth in vitro and in vivo through regulating miR-492/Klf5/Nrf1 axis and the cell apoptosis-related signaling pathways." (PMID 33413440, 2021). "Mechanically, metapristone regulated miR-492 and its new target genes Klf5 and Nrf1 in vitro and in vivo to treat endometrial cancer." (PMID 33413440, 2021). "Metapristone inhibited the endometrial cancer cell growth through regulating the cell apoptosis-related signaling pathway and decreasing the expression of miR-492 and its downstream target genes (Klf5 and Nrf1), which provided the theoretical basis in clinical treatment of endometrial cancer." (PMID 33413440, 2021).
gastric adenocarcinoma (4 papers, 2013 to 2023). "KLF5 expression increases in parallel with increasing severity of histologic lesions that comprise the cascade to gastric adenocarcinoma, which may provide insights into oncogenic events that develop in response to H. pylori infection." (PMID 23372710, 2013). "In gastric adenocarcinoma, increased promoter methylation of transcription factors CDX1/2 and KLF5, which are the downstream targets of the sonic hedgehog (SHH) signaling, caused reduced expression of CDX1 and KLF5 and elevated expression of CDX2." (PMID 36810098, 2023). "In gastric adenocarcinoma, significant DNA methylation of Shh transcription factors CDX1/2 and KLF5 correlated with decreased expression of CDX1 and KLF5 and an increased expression of CDX2." (PMID 35563709, 2022).
heart failure (4 papers, 2022 to 2026). Inability of the heart to pump blood at an adequate rate to meet tissue metabolic requirements. "Previous studies have illustrated that activation of cardiomyocyte Klf5 limits doxorubicin-induced heart failure by mediating glucose metabolism." (PMID 40822849, 2025). "Further research on KLF5 is still needed to provide a precise novel strategy for preventing and treating heart failure." (PMID 35457114, 2022). "Inhibition of KLF5, the positive transcriptional regulator of cardiac Ppara, leads to cardiac dysfunction, and cardiomyocyte-specific ablation of KLF5 decreases cardiac ATP and FAO levels, leading to cardiac insufficiency." (PMID 38516000, 2024).
intestinal cancer (4 papers, 2014 to 2023). "KLF5 functions as a cancer-promoting transcription factor in a variety of cancers, including breast, bladder, and intestinal cancers." (PMID 37063424, 2023).
ischemic stroke (4 papers, 2015 to 2022). A stroke disorder caused by obstruction of blood flow to the brain, due to thrombotic (local blood clot formation) or embolic (due to a blood clot or other material traveling from another site) event. "The inhibition of the KLF5-mediated JNK signaling pathway efficiently attenuates neuronal apoptosis in rats with ischemic stroke." (PMID 35883144, 2022). "Klf5 was significantly downregulated in the blood of rats with ischemic stroke obtained from the GSE21136." (PMID 36203804, 2022). "Similarly, miR-195 downregulated Kruppel-like factor 5 (KLF5) and blocked the JNK signalling pathway, ultimately inhibiting neuronal apoptosis in rats with ischaemic stroke." (PMID 33029119, 2020). "Additionally, a previous study revealed the negative role of Klf5 in neuronal apoptosis of ischemic stroke through the JNK pathway." (PMID 36203804, 2022).
pancreatic ductal adenocarcinoma (4 papers, 2020 to 2025). An infiltrating adenocarcinoma that arises from the epithelial cells of the pancreas. "In pancreatic ductal adenocarcinoma (PDAC), TGF-β inhibits the expression of major gastrointestinal spectrum regulator, Krüppel-like Factor 5 (KLF5)." (PMID 34335834, 2021). "A previous study showed that KLF5 disruption reduces STAT3 activation and tumor growth of pancreatic ductal adenocarcinoma in vivo." (PMID 33424607, 2020).
pulmonary artery hypertension (4 papers, 2011 to 2024). "Malat1 interacts with miR‐124‐3p.1/KLF5 to enhance the remodeling of pulmonary vasculature and facilitate the progression of cell cycle in pulmonary artery hypertension." (PMID 39491316, 2024). "KLF5‒HIF-1α interaction plays a vital role in the progression of hypoxia-induced pulmonary hypertension and pulmonary artery remodeling." (PMID 33493334, 2021). "It was previously discovered that the binding of miR-124-3p, MALAT1, and KLF5 could modulate pulmonary artery hypertension development, and MALAT1 was positively correlated to KLF5." (PMID 36243708, 2022). "KLF5 is also a target gene of metastasis-associated lung adenocarcinoma transcript 1 (MALAT1); the MALAT1/hsa-miroRNA (miR)-124-3p.1/KLF5 axis is pivotal in cell cycle progression of pulmonary artery hypertension." (PMID 33493334, 2021). "Nonetheless, the implication of KLF5 in pulmonary arterial hypertension (PAH) remains unknown." (PMID 21951574, 2011).
schizophrenia (4 papers, 2013 to 2024). A major psychotic disorder characterized by abnormalities in the perception or expression of reality. "The KLF5 gene encodes a member of the Kruppel-like factor subfamily of zinc-finger proteins, which is enriched in the motifs of transcription factors for schizophrenia." (PMID 35286190, 2022). "ZFHX3, RND3, KLF5, ERBB4, EGR1 and APC genes are both schizophrenia candidate genes and tumor suppression genes." (PMID 24564241, 2013).
type 2 diabetes (4 papers, 2018 to 2025). "The aim of this study was to investigate the effect of high performance (HP) inulin supplementation on glucose homeostasis via KLF5 mRNA expression in adults with type 2 diabetes." (PMID 29670837, 2018). "Based on these findings, it will be interesting to investigate whether specific targeting of Klf5 in pathological contexts, for example insulin resistance or type 2 diabetes, is sufficient to rectify lipotoxicity and improve lipid oxidation." (PMID 40250760, 2025). "Moreover, studies have shown that metformin, an anti-type 2 diabetes drug, leads to KLF5 degradation." (PMID 31401336, 2019). "As EAC is commonly co-morbid with type 2 diabetes, targeting KLF5 with metformin may represent a possible supplement to conventional EAC therapies." (PMID 31401336, 2019).
abdominal aortic aneurysm (3 papers, 2020 to 2025). Enlargement and ballooning of the vessel that supplies arterial blood to the abdomen, pelvis and legs. "Here, we show that Klf5 down-regulation in VSMCs is correlated with rupture of abdominal aortic aneurysm (AAA), an age-related vascular disease." (PMID 32817651, 2020). "Besides, KLF5-mediated Myo9b and downstream RhoA activation is involved in podosome formation and promotes macrophage migration during the development of abdominal aortic aneurysm." (PMID 33493334, 2021). "Down-regulation of Klf5, an essential transcriptional factor of cardiovascular remodeling, in vascular smooth muscle cells is correlated with vascular senescence and rupture of abdominal aortic aneurysm." (PMID 32817651, 2020). "In KLF5 knockdown mouse models, M2-type rather than M1-type macrophages are predominant in abdominal aortic aneurysm tissues, which exert an anti-inflammatory effect." (PMID 33493334, 2021).
Alzheimer disease (3 papers, 2021 to 2022). A progressive, neurodegenerative disease characterized by loss of function and death of nerve cells in several areas of the brain leading to loss of cognitive function such as memory and language. "In contrast, 17β-oestradiol inhibited the KLF5-NFκB inflammatory pathway in an Alzheimer’s disease mouse model." (PMID 36358467, 2022).